RUNX3 (RUNX family transcription factor 3)
Diseases named in the same sentence as RUNX3 in open-access papers (continued):
Sharing a sentence is not in itself a finding about the gene and the disease.
tumor (continued). "Given that RUNX3 is more commonly recognized as a tumor suppressor gene, it is more suitable to be developed as a diagnostic marker for solid cancers." (PMID 36429115, 2022). "Further studies in murine gastric epithelium revealed that RUNX3 functions as a tumor-suppressor downstream of TGFβ signaling and forms a protein complex with SMADs to induce the expression of the cyclin-dependent kinase inhibitory protein-1 p21waf1/cip1." (PMID 36231078, 2022). "Measurements of the expression of RUNX3 and E-cadherin mRNAs in mouse tumor tissues also indicated greater expression of these genes in mice that received the OE cells." (PMID 36518886, 2022). "RUNX3 is well-established as a putative tumor suppressor due to its ability to regulate the expression of a series of target genes, while RUNX3 down-regulation can induce the progression of GC." (PMID 35272674, 2022). "Tumor stage analysis showed that the P16 promoter was methylated only in stage T2 tumors (8% vs. 0%; p = 0.041), while promoter hypermethylation of RUNX3 was significantly more common in cases with affected nodes (52% vs. 31%; p = 0.032)." (PMID 36499753, 2022). "The RUNX3 gene has been described as both a tumor suppressor and promoter, sometimes with contradicting results in the same type of tumor, which most likely reflects the complex role of this gene and its encoded factor in oncogenesis." (PMID 36005134, 2022). "RUNX3, which serves as a mediator of multiple tumor suppressor pathways, is inactivated in KRAS mutant lung cancer." (PMID 36619616, 2022). "The tumor regulatory role of RUNX3 (runt-related transcription factor 3), the Wnt pathway antagonist, in OSCC is still controversial." (PMID 35571032, 2022). "A 2002 study reported that RUNX3 functioned as a tumor suppressor in gastric epithelial cells and that this gene was inactivated in up to 80% of primary gastric tumors." (PMID 36518886, 2022). "The expression of PAX7 and RUNX3 were similar between ES cell lines and were significantly higher in RD-ES cell line in comparison to other tumor cell lines (p < 0.01)." (PMID 33924679, 2021). "Taken together, we demonstrate that RUNX3 is a super-enhancer-associated gene only highly expressed in AML cells instead of in normal blood cells and probably exerts pro-tumor function on AML cells." (PMID 34722267, 2021). "G9a-mediated RUNX3 methylation thus can serve as a potential therapeutic target to prevent tumor growth by increasing cell proliferation and antiapotosis during early tumorigenesis." (PMID 33116296, 2021). "miR-130a-3p, on the other hand, has been described to act as an oncogene, promoting tumourigenesis by targeting tumour suppressor genes such as RUNX3 and PTEN." (PMID 34948097, 2021). "This methylation inhibit the transactivation activity of RUNX3 and thereby impairs its tumor suppressive functions." (PMID 33116296, 2021). "RUNX3 is described both as oncogene and tumor suppressor gene depending on the analyzed tumor entity or cellular background and readout." (PMID 33482905, 2021). "Nevertheless, subsequent functional analyses identified tumor suppressive functions for CAMK2N1 and a dichotomous role for RUNX3 transcript variants regulated by DNA methylation." (PMID 33482905, 2021). "Since overexpression of RUNX3 alone strongly slowed down tumor growth, we co-overexpressed G9a with RUNX3 WT or mutants." (PMID 33116296, 2021). "Second, we found that Runx3 re-expression abolishes the pulmonary metastasis of B16-F10 cells, but it slightly affects the subcutaneous tumor formation rate." (PMID 33672337, 2021). "In the ovary, similar contradicting findings describe RUNX3 as tumor suppressor, regulator of normal physiological development or an oncogene." (PMID 33530588, 2021).
tumor (continued). "Despite studies analyzing pre-invasive and invasive carcinomas, which were performed in diverse tumor types, the mechanisms by which aberrant RUNX3 expression impacts disease pathogenesis remains poorly understood." (PMID 33530588, 2021). "The mode of action of Runx3 in the suppression of tumor progression is complex, but evidence shows that Runx3 governs the EMT during tumor progression." (PMID 33672337, 2021). "Diverse PTMs affect tumor suppressive functions of RUNX3, such as stability, subcellular localization, and transactivation activity." (PMID 33116296, 2021). "RUNX3 is involved in various cellular functions and is described as both tumor suppressor and oncogene." (PMID 33530588, 2021). "Bledsoe and collaborators verified that RUNX3 is expressed in ES cell lines as well as in tumor biopsies." (PMID 33924679, 2021). "Runx3, a member of the Runx family of transcription factors, has been studied as a tumour suppressor and key player of organ development." (PMID 34611951, 2021). "Specifically, the genes of the identified best methylation marker combination CAMK2N1 and RUNX3 were shown to have tumor suppressive functions (CAMK2N1) or to be involved in platin resistance and migration (RUNX3)." (PMID 33482905, 2021). "It is intriguing that RUNX3 demonstrates both tumor-suppressive and oncogenic activities in multiple solid tumors." (PMID 32717065, 2020). "In this way, we also broaden our knowledge of RUNX3 as a tumour suppressor, and why its inadequate expression in nuclei contributes to tumour progression and relapse." (PMID 32307917, 2020). "In any case, RUNX3 is a key target for tumor therapy, and its specific molecular mechanisms need to be explored in the future." (PMID 33401247, 2020). "RUNX3 is reportedly inactivated in numerous types of tumors and is involved in various biological tumor processes, including epithelial-mesenchymal transition, adhesion, migration, and invasion." (PMID 33575207, 2020). "Compared to normal tissue, a significant increase in expression of RUNX3 mRNA in 31/57 patient’s tumor tissue (p < 0.04) was observed." (PMID 32943993, 2020). "The activity of RUNX3, a tumor suppressor, is inhibited in various cancers by mislocalization, hypermethylation, or loss of heterozygosity." (PMID 32731498, 2020). "Correlating to the observed up-regulation of mRNA expression in tumors, RUNX3 protein level was also found to be upregulated in IHC of tumor compared to normal tissues." (PMID 32943993, 2020). "According to previous reports, G9a activity increases, causing an increase in global histone methylation, and further cause transcriptional repression of different tumor suppressors, including CDH1, DUSP5, SPRY4, and RUNX3." (PMID 32015216, 2020). "Accordingly, higher mRNA levels of RCAN1.4 and RUNX3 were observed in normal tissues than in tumour breast tissues." (PMID 32771023, 2020). "The patients with tumours that had both low RUNX3 and RCAN1.4 protein expression had significantly shorter overall survival than those with tumours that had either high expression of RUNX3 or high expression of RCAN1.4." (PMID 32771023, 2020). "Fisher’s exact test showed that the patients with tumours that had both low RUNX3 and RCAN1.4 protein expression had the higher death rate than those with tumours that had either high expression of RUNX3 or high expression of RCAN1.4." (PMID 32771023, 2020). "To determine how RUNX3 inhibits cell migration and invasion, we focused on clarifying the relationship between RUNX3 and MMPs, which have been reported to participate in tumor progression." (PMID 32765634, 2020).
tumor (continued). "Another report showed that canonical BMP signaling induces the expression of RUNX3, which suppresses tumor growth by binding to the RUNX-binding elements on the c-Myc promoter and inhibiting its transcription." (PMID 32731498, 2020). "Only RUNX3 was identified and had an average methylation difference of 60.9% between primary tumour and NAT samples (n = 5)." (PMID 32971738, 2020). "HOTAIR can bind to RUNX3 protein, which functions as a tumor suppressor in multiple malignancies, and promote the interaction between RUNX3 and the E3 ubiquitin ligase MEX3B, inducing degradation via MEX3B-mediated ubiquitination." (PMID 32928281, 2020). "In our study, we found unmethylated CpG in RUNX3 in 47.36% (27/57) samples and out of these 27 samples 81.48% (22/27) samples showed elevated expression of the RUNX3 protein in the tumor as compared to the normal tissue." (PMID 32943993, 2020). "For example, known tumor suppressors or tumor-related genes (p16, RUNX3, MLH1, CDH1, etc.)are silenced by promoter methylation in GC and its precancerous lesions." (PMID 31959204, 2020). "RUNX3 has been shown to inhibit EMT, which encourages metastasis; by regulating these signaling pathways, RUNX3 plays a critical role in the regulation of tumor cell migration, invasion, and proliferation from epithelial to mesenchymal." (PMID 32765634, 2020). "Collectively, our results suggest that RUNX3-mediated CCL5 repression is critical for modulating anti-tumor immunity." (PMID 32218434, 2020). "Activation of the TrkB-mediated PI3K/AKT pathway decreases the expression of Runx3 and Keap1 tumor suppressors." (PMID 32340410, 2020). "Recently, the runt-related transcription factor 3 gene (RUNX3), belonging to the runt domain family of transcription factors, has gained attention for its role in tumor progression." (PMID 32943993, 2020). "Runx3, a tumor suppressor, is upregulated after miR-106b suppression, and the inhibition of Y79 cell proliferation is seen, which suggests that Runx3 is a target of miR-106b in an RB." (PMID 32992741, 2020). "The other explanation for RUNX3 up-regulation emanates from the possibility of adaptation of cells to over-express RUNX3, as a tumor suppressor gene, to counter the induction of cancer." (PMID 32943993, 2020). "Runt‐related transcription factor functions as a tumor suppressor, and the gene (RUNX3) is frequently deleted or transcriptionally silenced in cancer." (PMID 32783304, 2020). "Meanwhile, high intratumoral vascularity, unclear margins, and a left-sided tumor can be used to predict high RUNX3 methylation level." (PMID 33575207, 2020). "RUNX3 is an interpretation factor known for its tumor suppressor activity and lately has been involved in malignant growth metastasis." (PMID 32765634, 2020). "Overall, our results show that miR-301a promotes lung tumorigenesis via RUNX3 directly involving tumor cell metastasis and the tumor immune response events." (PMID 31122259, 2019). "RUNX3 has been variously described as a tumour suppressor or promoter, occasionally with a conflicting result in the same cancer and possible reflecting a complex role of RUNX3 in oncogenesis." (PMID 31467531, 2019). "As a downstream effector of the transforming growth factor-β (TGF-β), RUNX3 play a critical role in regulation of tumor cell migration, invasion, and epithelial-to-mesenchymal transition (EMT)." (PMID 31122259, 2019). "Blockade of Runx3 expression sharply increased tumor metastasis, accompanied by fewer tumor-infiltrating CD4+ and CD8+ T cells." (PMID 31122259, 2019). "Our findings further underscore that miR-301a facilitates tumor microenvironment antitumor immunity by Runx3 suppression in lung tumorigenesis." (PMID 31122259, 2019).
tumor (continued). "As a result, runt‐related transcription factor 3 (RUNX3), a well‐known tumor suppressor in HCC, was predicted to be a hypothetic target gene of miR‐106b‐5p in this malignancy." (PMID 31503422, 2019). "Loss of miR-301a in lung tumor cells inhibits tumor metastasis by targeting RUNX3, whereas deletion of miR-301a in tumor microenvironment reduces the tumorigenesis by elevating CD8+ cytotoxic T cells by negatively regulating RUNX3." (PMID 31122259, 2019). "TOX is a transcription factor involved in CD4+ T-cell development with downstream effects on RUNX3, a known tumor suppressor gene." (PMID 31139323, 2019). "We found significantly higher Runx3 expression in tumor-infiltrating immune cells isolated from B16 tumors from miR-301a−/− mice compared to those from WT mice." (PMID 31122259, 2019). "Recent studies have found that the overexpression of RUNX3 in ENKL, and myc transcriptional regulated RUNX3 by binding with it, sequentially resulted in increased proliferation of tumor cells." (PMID 31139570, 2019). "The function of miR-301a/Runx3 in regulating tumor microenvironment and tumor metastasis were evaluated in Kras transgenic mice and B16/LLC1 syngeneic xenografts tumor models." (PMID 31122259, 2019). "Because TOX is a transcription factor, we sought to examine expression of its known downstream targets, particularly RUNX3, a tumor suppressor gene frequently deleted or transcriptionally silenced in cancer." (PMID 31139323, 2019). "Nevertheless, other studies showed opposite data and suggested tumour promoting or oncogenic role for RUNX3." (PMID 31467531, 2019). "Down-regulation of Runx3 by shRNA in B16 metastatic tumors grown in miR-301a−/− mice increases the amounts of tumor-infiltrating CD8+ T cells and reduces lung metastasis." (PMID 31122259, 2019). "S1D), indicating that Runx3 compensated for the tumor growth upon conditional inactivation of Runx1 in the Nf1fl/fl;DhhCre cells." (PMID 31032403, 2019). "In a 3-year follow-up study after resection of the primary tumour, the preoperative methylated levels of RUNX3 of 52 patients with recurrence were significantly higher than that of 292 patients without recurrence (P = 0.0003)." (PMID 30944663, 2019). "In accordance with clinical data showing promoter P2 hypermethylation in patients with poor prognosis, RUNX3 TV2 can be labelled as the more tumor suppressive version." (PMID 29342962, 2018). "Pretreatment of the cancer cells by the methylation inhibitor, 5-aza-2′-deoxycytidine before inoculation decreased the tumor size, extended the animal survival time with decreased methylation of CpG islands in the promoters of RUNX3 and TGF-β." (PMID 29651226, 2018). "In cancer, Runx3 is commonly deleted or transcriptionally silenced as a tumor suppressor, which also regulates positional variations in axon extension properties without disturbing nerve guidance and branching." (PMID 30038556, 2018). "RUNX3 is described to exert tissue-specific functions leading to both oncogenic and tumor-suppressive roles depending on analyzed tumor entities." (PMID 29342962, 2018). "In contrast, when anti-tumor CD8+ T cells overexpressing Runx3 were transferred in vivo, tumor growth was inhibited, and mouse survival improved." (PMID 30180905, 2018).
tumor (continued). "For example, Lee and colleagues showed that the combination of miR-130a and miR-495 produced a greater decrease in the expression of the tumor suppressor RUNX3, than either miRNA alone." (PMID 29698509, 2018). "By contrast, when antitumor CD8+ T cells that overexpress Runx3 were transferred in vivo, tumor growth was inhibited, and mice survival improved." (PMID 30100906, 2018). "Our previous study demonstrated that RUNX3 protein is mainly expressed in nucleus and cytoplasm of acinous cells and ductal cells in normal salivary gland, but only in cytoplasm of tumor cells in SACC." (PMID 29467592, 2018). "Using a similar transplantable melanoma model, another study demonstrated a CD8 T cell-intrinsic requirement for the transcription factor Runx3 in the development of tumor-resident CTL responses." (PMID 30298068, 2018). "Attenuation of RUNX3 levels once the metastatic niche is established, switching the metastatic tumor to the locally proliferative state, would be an attractive explanation for this observation; however, experimental evidence would be required to support this." (PMID 29100342, 2017). "Conversely, CLAUDIN-1 exhibited tumor suppressive activity and mediated the tumor suppressor function of transcription factor RUNX3 in gastric cancer cells." (PMID 28617312, 2017). "Firstly, we used immunohistochemical (IHC) staining RUNX3 expression in cancer tissues and matched non-tumor tissues." (PMID 28977878, 2017). "RUNX3 binds R-Smads, co-Smads and p300, a transcriptional co-activator, and fulfills its tumor suppressor activity via TGF-β signaling pathway." (PMID 27825140, 2017). "Runt-related transcription factor 3 (RUNX3) has been reported as a tumor suppressor in some kinds of cancers." (PMID 28977878, 2017). "When GC was compared to non-tumor controls in the blood, significant heterogeneity was detected in the p16, RUNX3, and APC genes (P < 0.1)." (PMID 29100425, 2017). "Since then, RUNX3 has been observed as a suppressor that is inactivated in a variety of pre-invasive and invasive tumor including BC." (PMID 27825140, 2017). "RUNX3 expression is often found in many types of cancers, and plays a tumor suppressor role in cancer development." (PMID 28977878, 2017). "The immunohistochemical analysis revealed that Ki67 as a proliferation marker and CD31 as an endothelial cell marker were highly expressed in the tumor tissues of shCTRL cell-injected mice, but RUNX3 knockdown decreased the expression levels of these markers." (PMID 28030842, 2017). "RUNX3 contributes to tumor initiation and metastasis in different biological behaviors, including EMT, proliferation, migration and invasion." (PMID 28977878, 2017). "Together all these results suggested that RUNX3 play a vital role in FOXP3 transcription in tumor-CD8+ Treg by enhancing the promoter activity." (PMID 28487507, 2017). "Next, we used univariate and multivariate Cox regression model to determine significant factors, including RUNX3 expression, tumor volume, age, and TNM stage." (PMID 28977878, 2017). "Tumor growth and the generation of osteolytic lesions were significantly inhibited in mice that were subcutaneously inoculated with RUNX3-knockdown human OSCC cells." (PMID 28030842, 2017). "Accordingly, In many experiments the co-expression of SMAD3 or SMAD4 (the important proteins in TGF-β signaling) or TGF-β with RUNX3 has been exploited to reinforce RUNX3 efficiency in inhibition of tumor growth." (PMID 29201108, 2017). "We observed that lungs in LV5-RUNX3 nude mice had fewer and smaller detectable tumor nodules than control, indicating that RUNX3 reduces metastasis in nude mice model." (PMID 28977878, 2017).